LCIIAR (lung cancer immune cell infiltration associated lncRNA)
Gene: Long non-coding RNA gene on chromosome 15 (29,664,498 to 29,705,804, forward strand). Ensembl gene ENSG00000256802.
Diseases named in the same sentence as LCIIAR in open-access papers:
LCIIAR is named in the same sentence as 4 diseases in open-access papers, as found by Europe PMC text mining. Sharing a sentence is not in itself a finding about the gene and the disease. The quoted sentences say what the papers report.
lung adenocarcinoma (1 paper, 2022). A carcinoma that arises from the lung and is characterized by the presence of malignant glandular epithelial cells. "Therefore our findings revealed the critical role of LCIIAR in Lung Adenocarcinoma progression, which may also serve as a prognostic biomarker and novel therapeutic target." (PMID 35860557, 2022). "However, the clinical significance and functional role of LCIIAR in Lung Adenocarcinoma remain unclear." (PMID 35860557, 2022).
lung carcinoma (1 paper, 2022). "The Multivariate analysis showed that high expression of LCIIAR is associated with a more aggressive, metastatic stage of lung cancer, and with poor patient outcome." (PMID 35860557, 2022). "Finally, GEO dataset also show that higher expression of LCIIAR was correlated with adverse clinical outcomes in lung cancer patients." (PMID 35860557, 2022). "In the current work, we mainly investigated the function of LCIIAR in lung cancer." (PMID 35860557, 2022).
tumor (2 papers, 2022 to 2025). "Similarly, CASC2 and LCIIAR showed hypermethylation events that, in various cancers, are linked to aberrant cell proliferation and tumor progression." (PMID 40566344, 2025). "More importantly, we confirmed that silencing of LCIIAR expression significantly inhibits the proliferation, and migration abilities of these tumour cells." (PMID 35860557, 2022). "LncRNAs such as GACAT3, DELEC1, CASC2, and LCIIAR exhibited altered methylation status under PFOS exposure, suggesting potential disruption of tumor-suppressive functions or promotion of malignant phenotypes." (PMID 40566344, 2025).
cancer (1 paper, 2022). A tumor composed of atypical neoplastic, often pleomorphic cells that invade other tissues. "To examine the LCIIAR expression in pan-cancer, we examine the expression of LCIIAR in pan-cancer by using TCGA datasets and found that lncRNA LCIIAR was differentially expression between cancer and adjacent normal tissues or GTEx database normal tissue." (PMID 35860557, 2022).